TIMP2 (TIMP metallopeptidase inhibitor 2)
Diseases named in the same sentence as TIMP2 in open-access papers (continued):
Sharing a sentence is not in itself a finding about the gene and the disease.
aneurysm (6 papers, 2014 to 2024). Bulging or ballooning in an area of an artery secondary to arterial wall weakening. "TIMP-2 levels were significantly higher in the posterior part of the aneurysms associated with BAV (p=0.009)." (PMID 33029391, 2020). "On the other hand, TIMP 2 showed clear differences in the intima and adventitia, but TIMP2 was found to increase in the intima in the case of aneurysm and TIMP2 in the adventitia in the case of dissection." (PMID 38540232, 2024). "Our BAV Pro-MMP-2, total MMP-2, and TIMP-2 findings comparing the aneurysm's anterior and posterior parts concur with this hypothesis." (PMID 33029391, 2020). "On the other hand, if our finding of lower TIMP-2 levels in aneurysm than in control tissue potentially indicates levels too low to activate MMP-2, those can be seen as a hypothesis-generating finding also." (PMID 30794673, 2019). "Interestingly, the highest TIMP2 expression was measured in the intima in the case of aneurysms." (PMID 38540232, 2024). "However, TIMP-2 in the aneurysm could be downregulated to increase MMP-2 activation, whereas TIMP-2's inhibitory function is predominant in controls." (PMID 30794673, 2019). "Regression analyses showed that only the p-values of the regression coefficients in aneurysms < 5.5 cm depicted a linear relationship between active MMP-2 and TIMP-2 (p = 0.002), as well as between active MMP-2 and MMP-14/TIMP-2 ratio (p = 0.024)." (PMID 30794673, 2019). "Our ELISA results in the aneurysm group revealed that mean MMP-14 measured 3.55 ng/mL (SD 1,22) and mean TIMP-2 22.77 ng/mL (SD 7.99), whereas in the control group mean MMP-14 measured 3.71 ng/mL (SD 0.84) and mean TIMP-2 30.94 ng/mL (12.40)." (PMID 30794673, 2019). "The local tissue's MMP-14/TIMP-2 ratio may regulate the degree of Pro-MMP-2 activation in human aTAA as a determining factor, but MMP-14 and TIMP-2 do not seem to be enzymatically essential to aneurysm development." (PMID 30794673, 2019). "The tissue's MMP-14/TIMP-2 ratio may regulate the degree of Pro-MMP-2 activation as a determining factor, while the enzymatic activities of MMP-14 and TIMP-2 do not seem to play a key role in aneurysm development." (PMID 30794673, 2019). "On the other hand, MMP-14, TIMP-2 and their ratio in ROC curve are negligible compared to that of MMP-2, enabling us to hypothesize that the enzymes that activate MMP-2 are not the determining enzymatic factor in aneurysm development, rather that they support the central role of MMP-2 activation." (PMID 30794673, 2019).
cardiac hypertrophy (6 papers, 2013 to 2023). "In mice, deficiency of TIMP2 leads to increased cardiac hypertrophy and subsequent heart enlargement." (PMID 37893967, 2023). "The abnormal production of tissue inhibitor of matrix metalloproteinases type 2 (TIMP2) might repair myocardial functions which resulted in cardiac hypertrophy." (PMID 33328989, 2020). "The mRNA expression of cardiac hypertrophy markers (ANP, βMHC and TIMP2) was detected by RT-qPCR, and the results demonstrated that silenced ERK decreased the expression of ANP, βMHC and TIMP2 (p < 0.05)." (PMID 31649814, 2019). "Meanwhile, the expression levels of markers of cardiac hypertrophy (ANP, βMHC and TIMP2) were quantified through the performance of RT-qPCR." (PMID 31649814, 2019). "Next, RT-qPCR was performed in order to verify the expression of markers of cardiac hypertrophy (ANP, βMHC and TIMP2)." (PMID 31649814, 2019). "Clinical studies have shown that myocardial TIMP-1 and TIMP-2 mRNA expression is increased in patients with aortic stenosis, and myocardial MMP-1 and TIMP-1 protein expression is increased in patients with myocardial hypertrophy." (PMID 25861361, 2015). "Moreover, in order to quantify the cardiac hypertrophy and fibrosis degree of cardiac fibroblasts, the expression levels of markers of cardiac hypertrophy (ANP, βMHC and TIMP2) and markers of fibrosis (collagen I, collagen III and TGF-β) were evaluated." (PMID 31649814, 2019).
colorectal tumors (6 papers, 2002 to 2023). "The decrease of serum MMP-2 and TIMP-2 in more advanced tumor stages might be caused by the formation of MMP–TIMP complexes in colorectal tumor progression." (PMID 24395652, 2014). "To validate the relationship between 5-Fu resistance and TIMP-2 protein expression levels in colorectal tumors, we used small interfering RNA (siRNA) to knock down TIMP-2 expression in cell lines." (PMID 35022331, 2022). "Li and coworkers have shown that the imbalance between MMP-2 activity and its specific inhibitor TIMP-2 in colorectal tumor tissue might be a significant factor in the process of cancer invasion and metastasis." (PMID 24395652, 2014). "However, in a recent study it is shown that the level of TIMP-2 protein, when measured with ELISA, is significantly lower in colorectal tumours than in normal mucosa." (PMID 12085179, 2002). "Although TIMP-2 has been associated with large tumor size and high invasiveness in PTC, positive TIMP-2 staining is significantly higher in localized colorectal tumors and negative in the invasive forms." (PMID 24527080, 2014). "Here, we evaluated the prevalence of hypermethylation in the CDH1, CDKN2A, DAPK, and TIMP2 suppressor tumors genes of colorectal tumors tissue and their non-neoplastic adjacent margin using methylation specific PCR (MSP), which is a highly sensitive and specific technique." (PMID 26363785, 2015).
emphysema (6 papers, 2006 to 2020). "In particular, polymorphisms in MMP9 and TGFB1 are proposed to protect against centrilobular emphysema, and polymorphisms in TIMP2 and TNF seem to increase the risk for paraseptal emphysema and/or airflow obstruction." (PMID 23734748, 2013). "The TIMP2 rs2277698 was associated with emphysema sum score (p = 0.022) and paraseptal emphysema (p = 0.010)." (PMID 23734748, 2013). "In our study, the TIMP2 rs2277698 SNP was associated with overall and paraceptal emphysema, FEV1/FVC ratio, and MEF50." (PMID 23734748, 2013). "The TIMP2 rs2277698 SNP was associated with overall (p = 0.022) and paraseptal (p = 0.010) emphysema, as well as with FEV1/FVC ratio (p = 0.035) and MEF50 (p = 0.008)." (PMID 23734748, 2013). "TIMP-3 null mice develop emphysema while human studies show TIMP-1 and -2 are raised in the airways of COPD subjects and TIMP-2 polymorphisms are associated with CLE." (PMID 27460105, 2016). "We found significantly increased TIMP-2 and TIMP-4 in COPD subjects and also found that TIMP-4 had positive associations with several emphysema sub-types." (PMID 27460105, 2016). "Although TIMP2 polymorphisms have previously been connected to COPD, their association to different emphysema subtypes has remained unexplored." (PMID 23734748, 2013). "The contribution of various MMP's, TIMP1 and TIMP2 to emphysema have been investigated, and a key role for the MMP2-TIMP2 system proposed." (PMID 17054776, 2006).
Hyperglycemia (6 papers, 2013 to 2023). An increased concentration of glucose in the blood. "Indeed, chronic hyperglycaemia is known to up-regulate various pro-fibrotic genes in the diabetic heart as a whole, including Col1a1, Postn, Timp-2 and Ccn2." (PMID 34074290, 2021). "Additionally hyperglycemia is reported to decrease the expression of tissue inhibitor of MMPs i.e. TIMP-2 in trophoblast cells." (PMID 24376824, 2013). "Results showed that the hyperglycemia-induced GAG alterations in the cell surface perlecan as well as in the ECM indeed upregulated the expressions of IL-6, IL-8, and MCP-1 and the activities of MMP-2 and MMP-9 and downregulated the expressions of TIMP-2." (PMID 23983782, 2013).
liver cancer (6 papers, 2014 to 2022). An epithelial or non-epithelial malignant neoplasm that arises from the liver. "In addition, high expression levels of TIMP-2 in tumor tissues and serum of liver cancer patients were associated with decreased metastases." (PMID 35022331, 2022). "Besides, TIMP2 mutation frequencies are the highest in liver cancer, BRCA, and mesothelioma." (PMID 36304987, 2022).
liver disease (6 papers, 2013 to 2024). "Both TIMP-1 and TIMP-2 had significant diagnostic ability in detecting advanced liver disease but the status of TIMP-1 and TIMP-2, in the algorithm of NAFLD diagnosis, is yet to be established." (PMID 35743260, 2022). "Enhanced expression of TIMP-1 and TIMP-2 occurs in rat models of liver injury and in various human liver diseases." (PMID 23516586, 2013). "However, despite negative result, this is the first study testing the usefulness of urine [TIMP-2]·[IGFBP7] as an early biomarker of AKI in advanced liver disease patients." (PMID 31601879, 2019). "TIMP-1 and TIMP-2 are mainly produced by HSCs and are upregulated in various human liver diseases." (PMID 29986685, 2018). "Serum TIMP-2 and liver TIMP-2 mRNA are also increased in HCV induced liver disease." (PMID 23516586, 2013).
lymphoma (6 papers, 2013 to 2022). A malignant (clonal) proliferation of B- lymphocytes or T- lymphocytes which involves the lymph nodes, bone marrow and/or extranodal sites. "The Oncomine database showed that TIMP2 mRNA levels were significantly upregulated in nine cancer datasets, especially lymphoma (15 reported)." (PMID 36304987, 2022). "Four years later, the same team published a manuscript in which MMP-2/TIMP-2 complex levels were measured in plasma obtained from 126 patients with lymphomas (HL = 31, non-Hodgkin lymphoma (NHL) = 95) and 44 healthy controls." (PMID 32751899, 2020). "Coculture of M(IFN-γ/LPS) macrophages with apoptotic lymphoma cells significantly increased the expression of Mrc1, Timp2, Cd36, Pparg and Gas6, whereas the expression of Tnf and Il6 were significantly decreased." (PMID 28157210, 2017). "MMP-2 and TIMP-2 mRNA levels in the healthy control lymph nodes were significantly higher than in lymphomas (p<0.05)." (PMID 23641796, 2013). "Only in the case of Timp2 could untreated lymphoma cell cultures, of which approximately half the cells would undergo apoptosis during the course of the assay, also upregulate Timp2 expression." (PMID 28157210, 2017). "The TIMP-2 expression was examined, and the researchers observed TIMP-2 expression exclusively in lymphomas." (PMID 32751899, 2020). "Patients with newly diagnosed, active lymphoma had higher levels of MMP-2/TIMP-2 complex and lower levels of TIMP-2, compared to healthy individuals." (PMID 32751899, 2020). "The upregulation of Gas6, Mrc1, Cd36 and Timp2 expression by M(IFN-γ/LPS) macrophages was specific for coculture with apoptotic cells, as coculture with unstimulated or Bcl-2-transfected lymphoma cells did not lead to a significant upregulation of these genes." (PMID 28157210, 2017).
multiple sclerosis (6 papers, 2012 to 2023). A progressive autoimmune disorder affecting the central nervous system resulting in demyelination. "Additionally, Timp2 and Nos1 are assumed to be involved in the pathogenesis of multiple sclerosis." (PMID 36817487, 2023).
Myocardial fibrosis (6 papers, 2015 to 2025). "In particular, the TGF-β2–mediated imbalance of MMP2 and TIMP2 also contributes to myocardial fibrosis." (PMID 35115938, 2021). "In the aortic banding mouse model, TIMP2 knockout resulted in very poor left ventricular function and significant myocardial fibrosis." (PMID 31182988, 2019). "The results showed that maternal inflammation can induce myocardial fibrosis in offspring during aging accompanied by an imbalance of TIMP-2/MMP2 and TGFβ expression." (PMID 26006233, 2015). "IGF2 may also be involved in the progression of myocardial fibrosis by disrupting the TIMP2/MMP9 balance." (PMID 39744430, 2025). "Furthermore, as for the balance between MMP2 and TIMP2, the decrease in MMP2/TIMP2 also verified the heavier myocardial fibrosis in maternal PH rat offspring at 14 weeks of age." (PMID 35115938, 2021).
oral squamous cell carcinoma (6 papers, 2012 to 2026). "MiR-205-5p was found to suppress the invasiveness of oral squamous cell carcinoma by inhibiting tissue inhibitor of metalloproteinase 2 (TIMP2) expression." (PMID 33806361, 2021).
periodontitis (6 papers, 2020 to 2025). An acute or chronic inflammatory process that affects the tissues that surround and support the teeth. "It was suggested that MMP-2 T-790G, MMP-9 C-1562T, and TIMP-2 G-418C gene polymorphisms might be associated with periodontitis in the Taiwanese Han population." (PMID 35454140, 2022). "The biomarkers that decreased after SRP and OHI in periodontitis patients were IL-1β, MMP-8, MMP-9, PGE2, and TIMP-2." (PMID 33383828, 2020). "Biomarkers that decreased after scaling and root planning (SRP) and oral hygiene instruction (OHI) in periodontitis patients were IL-1β, MMP-8, MMP-9, prostaglandin E2 (PGE2), and TIMP-2." (PMID 33383828, 2020). "This study evaluated the gene expression of IL-1ß, IL-6, TNF-α, MMP-1, MMP-2, MMP-8, MMP-9, TIMP-1, and TIMP-2 in the gingival tissue of individuals with periodontitis or peri-implantitis compared to individuals without periodontal or peri-implant disease." (PMID 33291232, 2020). "Although PoPEx increased the expression of both MMP-3 and TIMP-2 in LPS-stimulated P-GMSCs, the MMP-3/TIMP-2 ratio was lower than the index in only LPS-stimulated P-GMSC cultures, suggesting that PoPEx tends to restrict tissue destruction in chronic periodontitis." (PMID 37895087, 2023).
triple-negative breast carcinoma (6 papers, 2021 to 2025). An invasive breast carcinoma which is negative for expression of estrogen receptor (ER), progesterone receptor (PR), and human epidermal growth factor receptor 2 (HER2). "Additionally, TIMP2 was significantly associated with age, estrogen receptor status, basal-like group, triple-negative breast cancer, PAM50 subtypes, and RSSPC subtypes." (PMID 34678879, 2021). "The use of TIMP-2 in the treatment of triple-negative breast cancer has been shown to suppress the cellular pathways involved in tumor metastasis." (PMID 37176095, 2023). "TIMP2 was significantly up-regulated in ER-negative group (P = .0014), basal-like group and basal-like (P < .0001), and triple negative breast cancer group (P = .0060)." (PMID 34678879, 2021). "TIMP2 has been shown to suppress the growth and metastasis of triple-negative breast cancer in a murine model by disrupting Wnt and PI3K signaling." (PMID 34572749, 2021). "EZH2 inhibits the transcription of TIMP2, which boosts activities of MMP-2 and MMP-9, which in turn increases the invasive activity of triple-negative breast cancer cells." (PMID 35912155, 2022).
abdominal aortic aneurysm (5 papers, 2019 to 2025). Enlargement and ballooning of the vessel that supplies arterial blood to the abdomen, pelvis and legs. "The prevalence of the TIMP-2 -418CC genotype and C allele was associated with abdominal aortic aneurysm (AAA) patients." (PMID 31275061, 2019). "However, research has shown that these markers are not specific for the TAA, as their increased levels can be detected in abdominal aortic aneurysm (AAA) (MMP-3, MMP-8, MMP-12, and TIMP-3), kidney diseases (TIMP-2) or cancers (MMP-9, TIMP-1, and TIMP-2)." (PMID 39456956, 2024). "Contrary to these data, an observational study focused on the AKI development in patients who underwent abdominal aortic aneurysm repair showed that urinary concentration of TIMP2*IGFBP7 neither changed significantly at baseline nor post-operatively." (PMID 39596140, 2024).
aortic stenosis (5 papers, 2015 to 2022). Aortic valve stenosis is a aortic valve disease caused by the incomplete opening of the aortic valve. "High values of TIMP-2 were reported in patients with aortic stenosis and fibrosis-related diseases." (PMID 36551935, 2022). "A study evaluating atrial remodeling in aortic stenosis patients with chronic AF showed a decrease in the MMP16/TIMP4 ratio in patients with AF along with an increased serum TIMP1 and TIMP2 proteins." (PMID 36312240, 2022). "MMP2 degrades troponin I in IRI ischemia–reperfusion injury, while in aortic stenosis, TIMP1 and TIMP2 are related to fibrosis." (PMID 34449561, 2021). "This study indicates an atrial matrix remodeling in aortic stenosis patients with chronic AF submitted to valve replacement while suggesting TIMP1 and TIMP2 as biomarkers of disease, readily available with peripheral blood sampling." (PMID 33129260, 2020). "Atrial fibrillation patients with severe aortic stenosis present increased atrial fibrosis and collagen type III synthesis, with extracellular matrix remodelling demonstrated by a decrease in the MMP16/TIMP4 ratio, along with an increased serum TIMP1 and TIMP2 proteins." (PMID 33129260, 2020).
depression (5 papers, 2019 to 2024). "For all measured MMPs (MMP-9, MMP-2, MMP-7) and TIMP-2 in blood, increased gene expression was statistically more significant at the mRNA level in patients with depression as compared to control individuals." (PMID 35370878, 2022). "Interestingly, transcript and protein levels of MMP-2, MMP-9 and TIMP-2 were found to be downregulated in patients with the recurrent depressive disorder as compared to healthy individuals." (PMID 31172215, 2019). "Moreover, reduced mRNA and protein levels of MMP-2, MMP-9 and TIMP-2 were observed in patients diagnosed with depression and displaying lower performance in cognitive tasks, as compared to healthy subjects." (PMID 31172215, 2019).
endothelial dysfunction (5 papers, 2022 to 2025). In vascular diseases, endothelial dysfunction is a systemic pathological state of the endothelium (the inner lining of blood vessels) and can be broadly defined as an imbalance between vasodilating and vasoconstricting substances produced by (or acting on) the endothelium. "The reduced levels of TGF-β1 and TIMP-2 may reflect endothelial dysfunction caused by the antitumor therapy." (PMID 36136069, 2022). "The rescue experiments illustrated that miR-483-5p downregulation can prevent endothelial dysfunction, and the mechanism is related to cell autophagy and the TIMP2 gene." (PMID 37891465, 2023). "The authors suggested that reduced serum TIMP-2 could potentially serve as an indicator for endothelial dysfunction resulting from anti-tumor therapy." (PMID 38276258, 2023). "Therefore, in light of the previous evidence and the present findings, we deduced that miR-483-5p downregulation might recover the endothelial dysfunction by promoting autophagic flux via targeting TIMP2." (PMID 37891465, 2023).
metabolic syndrome (5 papers, 2014 to 2024). A cluster of metabolic risk factors for CARDIOVASCULAR DISEASES and TYPE 2 DIABETES MELLITUS. "First, it was already mentioned earlier that circulating concentrations of TIMP1 (and TIMP2) are significantly increased in patients with metabolic syndrome (MeS), and these levels are even higher in the presence of diabetes." (PMID 37445827, 2023). "Levels of MMP2, MMP9, TIMP-1 and TIMP-2 are all increased in diabetic patients with dyslipidemia or with acute coronary syndrome." (PMID 25204377, 2014). "Our results demonstrated that there was a significant difference in TIMP-2 levels between obese people with and without metabolic syndrome and greater levels of TIMP-2 in those groups versus non-obese subjects were observed." (PMID 34625635, 2021). "In accordance with our results, higher TIMP-2 levels were detected in patients with metabolic syndrome versus non-obese people." (PMID 34625635, 2021). "The aim of this study is to investigate the plasma levels of MMP-1, MMP-2, MMP-3, MMP-9, TIMP-1, TIMP-2 and their ratios in a large variety of study groups including overweight people and obese people with or without metabolic syndrome and non-obese healthy people with total of 479 participants." (PMID 34625635, 2021).